WEE1 (WEE1 G2 checkpoint kinase)
Diseases named in the same sentence as WEE1 in open-access papers (continued):
Sharing a sentence is not in itself a finding about the gene and the disease.
cancer (continued). "Given the emergence of loss of IDH2 as an important event in various malignancies, these results suggest that cancer cells overexpressing WEE1 may epigenetically suppress the expression of IDH2 gene to prevent the formation of 5-hmC." (PMID 29290954, 2017). "Further, this decrease in IDH2 gene expression correlated with reduced 5-hmC levels, suggesting that the overexpression of WEE1 in cancer cells may suppress the expression of IDH2, leading to decreased 5-hmC levels." (PMID 29290954, 2017). "Wee1 kinase is an important regulator of the G2 checkpoint and is overexpressed in various cancers." (PMID 28978051, 2017). "The development and clinical use of Wee1 and Hipk1 kinase chemical inhibitors might be a promising strategy to improve anti-cancer therapy." (PMID 27077811, 2016). "By suggesting that Wee1 inhibitors could be beneficial in combination with AMCDs, our data may further expand our options for cancer treatment." (PMID 27670139, 2016). "We focused on the advantage of inhibiting WEE1 and how that may inhibit the epithelial-mesenchymal transition (EMT), which is associated with the metastasis of cancer." (PMID 27363019, 2016). "On the other hand, ATR, Chk1, and Wee1 are also overexpressed in a subset of human cancers." (PMID 25774168, 2015). "Consistent with this hypothesis, increased expression of ATR/Chk1/Wee1 kinases was reported in various cancer cell lines." (PMID 26295265, 2015). "This may, at least in part, explain the particularly effective synergism between Wee1 inhibitors and chemotherapeutics and encourage the clinical evaluation of Wee1 inhibitors in combination with conventional cancer treatment." (PMID 26124918, 2015). "WEE-1 is overexpressed in several cancers including primary AML, ALL, and CML specimens." (PMID 25914884, 2015). "Despite the simultaneous impairment of Chk1 activity by Wee1 inhibitors, combining inhibitors of Wee1 and Chk1 may nonetheless prove useful to eliminate cancer cells." (PMID 26124918, 2015). "Inhibitors of ATR, Chk1, or Wee1 may thus potentially be more toxic to cancer cells inherently expressing high levels of these kinases." (PMID 25774168, 2015). "Ablation of WEE1 and PKMYT1 expression can cause mitotic collapse and apoptosis of cancer cells." (PMID 25477524, 2015). "Here we show these cancers can be targeted by inhibition of WEE1." (PMID 26602815, 2015). "In addition, MCL cell lines were 10 and 6 times more sensitive to Chk1 and Wee1 inhibitors, respectively, than different epithelial carcinoma cell lines." (PMID 25428911, 2015). "Given the divergent reports on the expression of Wee1 in different cancer forms; the exact role of the kinase in cancer remains largely unknown." (PMID 23767999, 2013). "By preventing too high CDK activity during S-phase, Wee1 may forestall potentially lethal DNA damages from occurring in the cancer cells." (PMID 23767999, 2013). "Inhibiting proteins involved in the G2/M checkpoint, such as Wee1, may therefore selectively target cancer cells whilst sparing normal cells with a functional G1/S checkpoint." (PMID 23767999, 2013). "Wee1 is a central regulator of the G2/M DNA-damage checkpoint, and has in previous studies been described as a prognostic biomarker and a potential target for therapy in other cancer forms." (PMID 23767999, 2013).
cancer (continued). "Further studies will be needed to clarify the role of Wee1 as a prognostic marker in human cancer." (PMID 23767999, 2013). "In agreement with this hypothesis, inhibition of Wee1 has led to reduced proliferation in a range of cancer cell lines." (PMID 23767999, 2013). "The augmented expression of Wee1 may seem as a controversy in malignant tumors, based on its well-known inhibitory role in cell cycle progression." (PMID 22719872, 2012). "Thus, high expression of Wee1 appears to protect the cancer cell from DNA damage and ultimately cell death." (PMID 22719872, 2012). "High protein expression of Wee1 has previously been reported in human cancers." (PMID 22719872, 2012). "WEE1 could therefore be a strategic, cancer cell specific drug target and its inhibition could be an effective strategy to enhance the efficacy of radiotherapy in OS." (PMID 21529352, 2011). "Since CDC2 codes for CDK1, which is phosphorylated by WEE1, our results suggest a feedback loop that might be important for cancer." (PMID 21390271, 2011). "Previous reports have suggested that WEE1 inhibitors may act in a cancer-specific manner." (PMID 39335109, 2024). "They found UCA1 to be upregulated in A431 and CAL-39 cells following their exposure to cancer-associated fibroblasts (CAF)-derived exosomes, and CAF-derived exosomal UCA1 mediated DDP resistance to both cell lines by sponging miR-103a and upregulating mitosis inhibitor protein kinase WEE1." (PMID 38534790, 2024). "Importantly, Wee1 inhibitors are currently in clinical trials for cancer treatment." (PMID 38206091, 2024). "In addition, further investigation of predictive biomarkers is needed for the selection of patients with SETD2 alterations who may derive a response to WEE1 inhibitors alone or in combination with other cancer-directed therapies." (PMID 38920407, 2024). "Notably, some scholars have reported that the synergistic effect of WEE1 inhibitors and histone deacetylase inhibitors (HDACi) could block the DNA damage response (DDR), and WEE1 knockdown could significantly enhance the sensitivity of cancer cells to HDACi." (PMID 39619613, 2024). "In this review, we focus on inhibitors of Chk1 and Wee1 kinases and present the current biological evidence supporting their utility as radiosensitisers with different radiotherapy modalities, as well as clinical trials that have and are investigating their potential for cancer patient benefit." (PMID 39272874, 2024). "Here, we demonstrate that dual treatment with IAP and WEE1 inhibitors sensitizes both HPV-negative and HPV-positive HNSCC cells to both TNFα-dependent and radiation-associated cell death, demonstrating a potential therapeutic combination to treat these cancers." (PMID 36831373, 2023). "Additionally, cancers with a defective G1 checkpoint are dependent on their G2 checkpoint, showing that WEE1 inhibition may sensitize cancer cells to anti-cancer agents, including CHK1 inhibitors." (PMID 37627183, 2023). "In addition, WEE1, a nuclear kinase, is overexpressed in many cancers." (PMID 37370065, 2023). "Notably, Wee1 inhibition leads to increased eradication of tumor cells by cytotoxic T-lymphocyte through tumor necrosis factor (TNF)-α-dependent cell death in several cancer cells." (PMID 37296592, 2023).
cancer (continued). "Furthermore, several other mechanisms could lead to increased replication stress in cancer cells which would synergize with radiation and Wee1 inhibitor-mediated replication stress to endanger the survival of cancer cells entering mitosis." (PMID 35251998, 2022). "Therefore, several novel WEE1 inhibitors are undergoing preclinical tests in various cancer types." (PMID 36230796, 2022). "Indeed, cyclin E overexpression renders cancer cells sensitive to Wee1 inhibition." (PMID 35251998, 2022). "Therefore, Wee1 inhibition therapy could be used as an effective treatment for precancerous lesions to prevent cancer." (PMID 36338767, 2022). "This indicates that Wee1 may be important for cancer cells’ viability under specific circumstances." (PMID 34639030, 2021). "Therefore, disrupting PARP, ATM, ATR/CHK1, WEE1, or DNA-PK activity may selectively contribute to accumulation of DNA damage in tumors, sensitize cancer cells to killing, and ultimately induce cell death." (PMID 34930377, 2021). "WEE1 inhibition may therefore particularly expose cancer cells to DNA damage." (PMID 33552868, 2021). "In summary, in all the analysed cancer models, SLFN11 status was linked to outcomes from DDA treatments and the resistant SLFN11 low population could be re-sensitised to DDA by combinations with ATR, WEE1 or CHK inhibitors." (PMID 33339894, 2021). "Targeting Wee1 might be a therapeutic strategy for treating cancer." (PMID 34298699, 2021). "Therefore, we can speculate that, once the malignant transformation process has been induced, WEE1 upregulation exerts a pro-tumorigenic functions by securing a tolerable level of genomic instability to cancer cells." (PMID 32958072, 2020). "Hence, Wee1 inhibition monotherapy could well serve as chemopreventive strategy to eradicate precancerous changes and prevent cancer and local relapse." (PMID 32047167, 2020). "Importantly, combining Wee1 inhibitor to chemotherapy led to a larger retainment of platinum-sensitive cancer cells (29%) compared to the other combination therapies (3% and 2% for trientine and birinapant, respectively), consistent with the PFI benefit from this combination." (PMID 31822719, 2019). "Therefore, Wee1 has been thought as a promising therapeutic target for human cancers." (PMID 31427973, 2019). "Thus, our work highlights the importance of improved therapeutic strategies for patients with various cancer types and may explain why some patients respond better to WEE1 inhibitors." (PMID 30190546, 2019). "Therefore, targeting WEE1 has emerged as a promising therapy for human cancers." (PMID 30323762, 2018). "High expression of this protein is often found in cancers (colorectal cancers, breast cancers, leukemias and other cancers) and correlates with tumor progression and negative prognoses, despite the cell cycle-arresting activity of WEE1 before mitosis onset 42-44." (PMID 30540125, 2018). "Therefore, our findings suggest that Wee1 is a good molecular target for cancer therapy." (PMID 26804466, 2016).
cancer (continued). "Combined treatment with Chk1 and Wee1 inhibitors showed a strong synergistic cytotoxic effect in various human cancer cell lines suggesting that this combined target specific strategy could be a valid therapeutic approach against cancer." (PMID 26439697, 2015). "We hypothesized that loss of Wee1 in the absence of cytotoxics should be able to affect tumor cell proliferation because all metazoan cells, including cancer cells, rely on at least partially functioning checkpoints to insure their survival." (PMID 24927813, 2014). "First, replication stress–inducing agents, such as inhibitors of ATR, WEE1, and CHK1/2, are being explored in clinical trials with promising early results specifically in HR-proficient cancers." (PMID 40392598, 2025). "The goals are to generate patient-derived organoids (PDOs), xenografts (PDXs), and PDX-derived organoids (PDXOs), evaluate the therapeutic potential of the WEE1 inhibitor AZD1775, and compare their responses to 18 anti-cancer drugs in PDOs and PDXOs." (PMID 40551232, 2025). "Although WEE1, PLK1, and AURKA kinase inhibitors have been studied in HNSCC and other cancers, small molecule inhibitors targeting other G2/M kinases such as TTK are currently in preclinical or clinical development." (PMID 39392349, 2024). "On the other hand, WEE1 and AKT either compete, possibly due to GSK3 inhibition conferred by triciribine, or synergize through mechanisms similar to those reported in cancer cells." (PMID 39125637, 2024). "We have for the first time demonstrated reduction in the functional ability to repair DNA damage using cell free assays in cancer cells exposed to CHK1 and WEE1 inhibitors." (PMID 39516567, 2024). "Highlighting the significance of interactions with extracellular growth factors such as VEGFA and IGF1 in cancer growth and progression, several targets, including CCND1, WEE1, VEGFA, and CDK6, were identified to interact with two miRNAs." (PMID 39614097, 2024). "Their capacity to specifically attach to and possibly regulate the activity of proteins such as ATM, ATR, CHK1, and WEE1 reveals a pathway towards novel treatment approaches, emphasizing the essential role of DDR in the survival and growth of cancer cells." (PMID 38961104, 2024). "In the case of condylomatous lymphoma and diffuse large B‐cell lymphoma cancer cells, the CHK1 inhibitor AZD6738 and the Wee1 inhibitor AZD1775 delay S‐phase and accumulate DNA damage, and the synergistic impact of cytotoxicity is extremely apparent." (PMID 37808268, 2023). "Collectively, the data indicated a marked replication stress and replication catastrophe response to combined WEE1 and PKMYT1 inhibition that likely explains the major treatment lethality in cancer cells." (PMID 37325550, 2023). "Adavosertib and Wee1 inhibitors (Zn-C3; Debio 0123; SY4835; and IMP7068) are promising in ALL and other cancers as single and drug combination therapy as revealed by prior and ongoing clinical trials." (PMID 37633054, 2023). "Out of the eight cancer-related genes, we identified that pleural fluid GRB2, WEE1, RNF4, and DUSP6 mRNA levels were significantly different between patients with MPE and benign PE by using two-independent sample t-tests." (PMID 37095178, 2023). "The Wee1 inhibitor, MK-1775 (or AZD1775 or Adavosertib), promotes cancer cells to bypass G2/M checkpoint, leading to mitotic catastrophe." (PMID 36923534, 2023). "Wee1 inhibitors including adavosertib (MK-1775, AZD-1775) have been shown to overcome chemo-resistance in a variety of cancer models." (PMID 37633054, 2023). "Our study suggests that monocyte-derived biomarkers, specifically WEE1, PYHIN1, SEC61A2, and HAL, hold potential as predictors for cancer prognosis and AMI." (PMID 37781709, 2023). "The DDR pathways are promising targets for anti-cancer therapy, and various DDR-related genes are currently under clinical development, such as PARP, ATM, ATR, DNA-PK, CHK1, CHK2, and WEE1." (PMID 38041093, 2023).
cancer (continued). "Most important of all, these findings demonstrate the potential of utilizing shared biomarkers (WEE1, PYHIN1, SEC61A2, and HAL) to predict outcomes in both cancer and AMI patients." (PMID 37781709, 2023). "Inhibitors of WEE1, ATR, CHK1 and PLK1 have also achieved preliminary response in certain types of cancer patients." (PMID 37679326, 2023). "In our analysis, T‐ALL cell lines showed increased sensitivity to inhibitors of ATR (AZD6738, ceralasertib), CHK1/2 (AZD7762 and MK‐8776), and Wee1 (AZD1775, adavosertib) as measured by a reduced IC50 compared with other non‐T‐cell cancer cells." (PMID 35510955, 2022). "The combined decrease of Wee-1 and accumulation of pCDK (T14/Y15) by DOX is consistent with the inhibition of Wee-1 in cancer treatment reported in previous studies." (PMID 35053211, 2022). "Of special interest are the redundant and divergent roles of Wee1 and the related kinase PKMYT1, in normal tissues and in various cancer types." (PMID 35251998, 2022). "As expected, most genes in the cytotoxicity group were involved in cell cycle regulation, such as CCNB1 and WEE1, or are components in the ubiquitin–proteasome system (UPS), such as UBC and UBB, which are known to be active in cancer cells." (PMID 35459228, 2022). "Presumably, cancer cells exploit alterations of ATM/CHK2/p53to avoid cell cycle exit at the G1 phase and rely on ATR/CHK1/WEE1 activity to handle a high level of RS during continuous cell division." (PMID 36253861, 2022). "Combinations of pyridostatin with WEE1 and USP1 inhibitors have recently been reported to act synergistically in inhibiting growth of cancer cells in vitro." (PMID 35107878, 2022). "It was proposed that cancer stem cells, which often show increased chemo- and radiation resistance compared to bulk cancer cells and due to their cellular plasticity and tumor initiating capability can lead to tumor relapse, could be targeted by Wee1 inhibition." (PMID 35251998, 2022). "WEE1, which can inhibit the function of CDK1-cyclinB complex, is a potential target for cancer therapy." (PMID 35928440, 2022). "Inhibiting abnormally elevated Wee1 benefits CML therapy in both IM-resistant and IM-sensitive cells, manifesting various anti-cancer effects." (PMID 36575478, 2022). "It induced the DNA damage response kinase WEE1, and rendered human AML cell lines more resistant to cytosine arabinoside, daunorubicin, and other anti-cancer drugs." (PMID 33782537, 2021). "This synthetic lethality has been taken advantage of in several PARP inhibitor resistant cancer cases, targeting the ATR/CHK1/Wee1 signaling cascade." (PMID 33498235, 2021). "Both WEE1 and ATR inhibitors have been shown to radiosensitize cancer cells, and are in clinical testing together with ionizing radiation (IR)." (PMID 34359691, 2021). "Inhibitors of WEE1 and ATR kinases are considered promising for cancer treatment, either as monotherapy or in combination with chemo- or radiotherapy." (PMID 34359691, 2021). "There are currently multiple clinical trials utilizing this strategy inhibiting Wee1 and PARP with Olaparib (NCT04197713, NCT03579316, NCT03330847) in several cancer types." (PMID 33498235, 2021).